CD24 (CD24 molecule)
Diseases named in the same sentence as CD24 in open-access papers (continued):
Sharing a sentence is not in itself a finding about the gene and the disease.
cancer (continued). "It has been hypothesized that cancer cells utilize CD24 molecules to evade detection and attack by the immune system." (PMID 40510161, 2025). "CD24 functions as a signal preventing macrophage-mediated phagocytosis of cancer cells." (PMID 41551164, 2025). "Furthermore, pan-cancer analysis through TIMER2.0 demonstrated significantly higher CD24 expression in multiple malignancies relative to their corresponding normal tissues." (PMID 40830893, 2025). "Therefore, targeting CD24/Siglec-10 axis can improve prognosis of cancer patients both as anti-CD24/Siglec-10 monotherapy or in combination with other therapy approaches." (PMID 40835598, 2025). "Future studies may explore whether CD24-targeted therapies could promote the efficacy of immune checkpoint inhibitors and broaden the therapeutic scope of cancer immunotherapy across CD24-positive solid tumors." (PMID 40783744, 2025). "Both CD133 and CD24 are cancer stem cell markers applicable to other cancers as well." (PMID 40525700, 2025). "Anti‐CD24 treatment can still be effective in cancers that have been resistant to CD47 blockade." (PMID 41354057, 2025). "Mechanistically, CD44v6 influenced the expression of key CSC markers, including CD24, CD133, and EpCAM, which are known to be associated with cancer progression, stemness, and malignant behaviors like self-renewal, proliferation, migration, and chemoresistance." (PMID 40069421, 2025). "We saw significant transcriptional changes including the downregulation of key markers like EGR1 and CD24, whose reduced expression is linked to increased invasiveness and drug resistance and identified proteins such as TRIP6 and TRIM29 that enhance (cancer stem cells) CSC-like properties." (PMID 40946111, 2025). "Multiple trials have demonstrated that CD24 can serve as a cancer biomarker." (PMID 40486886, 2025). "Similarly, increased SOX9 and CD24 expressions in EEC were correlated with three cancer-specific differentially dREs in the malignant fraction." (PMID 39229264, 2024). "Based on these findings, we propose that CD24/SIGLEC10 could serve as a novel target for cancer immunotherapy, potentially enabling the investigation of monoclonal anti‐CD24 antibodies as a new treatment for NB." (PMID 40625458, 2024). "Recently, cytoplasmic CD24 has been observed in samples from patients with cancer." (PMID 39791710, 2024). "Future research focusing on the detailed mechanisms of CD24-mediated immune evasion and the development of innovative therapeutic agents targeting this pathway promises to enhance our arsenal against cancer, paving the way for more effective and precise immunotherapeutic interventions." (PMID 38881902, 2024). "Targeting CD24 could offer a more specific approach to enhancing phagocytosis of cancer cells compared to some other checkpoints, but it also faces challenges related to its complex biology and variability in expression." (PMID 38881902, 2024). "Investigating the therapeutic potential of these findings, we assessed whether PAC-SABIs could amplify the phagocytosis of cancer cells by diverse macrophage populations beyond direct anti-CD24 mAb or SAMIs blockade." (PMID 38971872, 2024). "This discovery suggests that the upregulation of CD24 in other cancers may indicate viral sensitivity, which could profoundly expand the pool of possible ZIKV therapy targets." (PMID 38214542, 2024). "Because of this intriguing function, CD24 is a novel target for cancer immunotherapy." (PMID 38702326, 2024). "Finally, we provide insights into potential clinical application of CD24 and discuss possible approaches for the development of targeted cancer therapies." (PMID 38881902, 2024).
cancer (continued). "Therefore, CD24 not only plays a regulatory role in normal immune function but also serves as a key player in cancer development, making it a potential target for cancer treatment and research." (PMID 38273373, 2024). "Recently, CD24 has been reported as a novel innate immune checkpoint in cancer." (PMID 38168654, 2024). "In pancreatic cancer, a highly tumorigenic subpopulation of cancer cells expressed CD24." (PMID 38360723, 2024). "Therefore, all parameters that were related to CD24 expression were significantly related to Gleason grade and cancer severity." (PMID 39687458, 2024). "Single-cell RNA-seq analysis of a primary BC sample, focusing on examining the expression patterns of CD47, CD24, CD274, SIRPα and Siglec-10 at the individual cell level, revealed a prominent expression of CD47 and CD24 in cancer cells, notably higher than that of CD274." (PMID 38971872, 2024). "The development of novel mAbs with high specificity and efficacy against glycosylation variations, CD24 peptides, BiTEs, CAR-T, and/or CD24-CAR NK cells could be among the tactics used in CD24/Siglec-10-targeted cancer immunotherapy in the future." (PMID 38279998, 2024). "Moreover, the loss of miR-125b and increased HIF-1α expression upregulate CD24 and erythropoietin, resulting in the enrichment of doxorubicin-resistant CD24+ cancer stem cell population." (PMID 39273339, 2024). "Additionally, the levels of ALDH and CD24−/CD44+/EpCAM+ cancer stem cell-like cell markers increased in breast cancer cells after chemotherapy, which helped cancer cells resist chemotherapy drugs and increase their stemness at the level of cell transcription." (PMID 38540708, 2024). "CD24 serves as a crucial marker for both the diagnosis and prognosis of cancer." (PMID 38881902, 2024). "The concept of employing bispecific antibodies (BsAbs) targeting both CD24 and PD-L1 could activate both innate and adaptive T cells immune responses, offering a more potent anti-cancer effect." (PMID 38881902, 2024). "Moreover, we observed the localization of CD24 in the nucleus of cancers, such as CESC, LUAD, HNSC, and STAD." (PMID 39791710, 2024). "Additionally, to evaluate the effect of HNF4A on the stemness of the spheroids, we screened for expression of cancer stem cell markers, including CD24, CD44, NESTIN, OCT4, and SOX2." (PMID 39165427, 2024). "However, the impact of the subcellular location of CD24 on the clinical prognosis of cancer remains controversial." (PMID 39791710, 2024). "In addition, since the cancer cell cluster C6 was characterized by concurrent enrichment of liver CSCs markers CD24, CD47 and ICAM1, we further sought to confirm the interaction between cluster C6 cancer cells and M2-like TAMs using TCGA-LIHC cohort." (PMID 38169544, 2024). "This overview of CD24 under normal physiological conditions elucidates the multifaceted roles it plays, highlighting the importance of understanding these fundamental processes to grasp the implications of CD24 dysregulation in disease states, notably in cancer." (PMID 38881902, 2024). "CD24 has been shown to play a role in drug resistance in cancer." (PMID 38881902, 2024). "In summarizing our study, CD133 was exclusively expressed in cancer cells compared to stromal and immune cells and was associated with other CSC markers (CD24, NOTCH1, DLL1, and ALDH1A1), as well as enriched WNT/β-Catenin, Hedgehog, and NOTCH signaling, validating CD133 as a CSC marker." (PMID 38585981, 2024). "As reprogramming to cancer stem cells’ state could potentially be indicative of the effect of senescent ASCs, we measured the levels of CD24, and CD44 after conditioning MCF10A1 cells with medium from ASCs and ASCs that were senesced." (PMID 38473331, 2024). "As recent studies suggest that CD24 may be a potential therapeutic target in cancer, the role of CD24 in SGTs warrants further investigation." (PMID 39858584, 2024).
cancer (continued). "Human cancer stem cells, a subpopulation of cells within tumors that have self-renewal capacity and the ability to differentiate into various cell types, appear to have decreased expression of CD24 compared to their offspring." (PMID 38881902, 2024). "CD24 has been found to be overexpressed in approximately 70% of human cancers." (PMID 39791710, 2024). "Strategies that target CD24 expression or function in cancer cells could enhance NKG2D-mediated immune responses, potentially overcoming immune evasion mechanisms and improving the efficacy of treatments designed to activate NK and T cells against cancer." (PMID 38881902, 2024). "Various anti-CD24-based cancer therapies have been evaluated in preclinical models." (PMID 37894750, 2023). "CD24 is similarly expressed across a range of cancers, with an emerging correlation with Ras." (PMID 38137380, 2023). "CD24-targeted cancer therapy in preclinical and clinical models." (PMID 37894750, 2023). "Gao and Wei observed the CD24 expression is relevant to the stemness of ovarian stem cancer cells." (PMID 37359556, 2023). "Therefore, CD24 is a potent and more appropriate anti-phagocytic “don’t eat me” signaling molecule that directly protects cancer cells from attack by Siglec-10-expressing macrophages." (PMID 37875918, 2023). "Interestingly, CD24 is uncorrelated to patient characteristics, not only among cancer patients, but also among healthy controls." (PMID 38138858, 2023). "Moreover, claudin-low cancers display low expression of epithelial surface molecules CD24 and EpCAM and high expression of CD44 and CD49f." (PMID 37345027, 2023). "Given the massive death of cancer cells and normal cells in immunotherapy and conventional cancer therapy, it is of interest to investigate whether irAE is regulated by CD24-Siglec interactions." (PMID 37228622, 2023). "CD24 is expressed on various cell types, including immune cells, neural cells, and cancer cells, and it is a glycosyl-phosphatidylinositol (GPI)-anchored protein with distinct domains: an intracellular domain, a transmembrane domain, and a heavily glycosylated extracellular domain." (PMID 38313430, 2023). "Further studies have indicated that CD24 may regulate cancer cell proliferation and invasion, supporting its usefulness as an intriguing target for novel therapies in different types of cancers." (PMID 37919766, 2023). "Targeting CD24 has been clinically accomplished in patients with cancer." (PMID 37894750, 2023). "Drug resistance, especially chemotherapy resistance remains to be the critical limiting factor in cancer treatment, in which CD24 may takes part." (PMID 37919766, 2023). "CD133 expression was present in a subpopulation of cancer cells from 1.1% to 18.0% with a median value of 6.5%; CD44 from 36.0% to 97.0% (median value 80.0%); and cells with CD24 expression consist of 0.0% to 16.0% (median value 7.0%) of the whole population of isolated cancer cells." (PMID 37958844, 2023). "CD24 emerges as a potential therapeutic target due to its important role in cancers." (PMID 36882399, 2023). "It is reported that integrase-derived peptides together with CD24-targeted lentiviral particles inhibit the growth of CD24 expressing cancer cells, which suggests that the CD24 could be an effective targeting tools for drug delivery." (PMID 37359556, 2023). "Above all, it is widely accepted that CD24 is playing vital role in cancer immunotherapy." (PMID 37359556, 2023). "It is hoped that, in the near future, cancer therapy targeted against CD24 may be a promising strategy for the treatment of solid cancers metastasis and recurrence in future." (PMID 37919766, 2023). "In conclusion, highly expressed CD24 in solid cancers appear to be both a prognostic biomarker as well as a promising therapeutic target, thus an opportunity is offered for researchers to study and use it in cancer treatment research and drug development." (PMID 37919766, 2023).
cancer (continued). "Therefore, this study reported that circulating cancer stem cells from patients with cancer (tumospheres positive for EpCAM and CD 44 +, and CD24− or CD24 low and positive ALDH1 activity) can be implanted in the CAM to generate tumors." (PMID 37834193, 2023). "Secondly, CD24 may enhance the proliferation and survival of cancer cells through the Src/STAT3 pathway." (PMID 38137380, 2023). "Recent studies have demonstrated that increased CD24 levels in the blood might be a new prognostic indicator and a biomarker for early cancer detection." (PMID 38313430, 2023). "Double reactivity with another cancer stem cell marker, e.g., CD24 or CD133, would be necessary." (PMID 37108193, 2023). "Moreover, high CNV cancer cells were found to express higher CD24 than low CNV cancer cells and fibroblasts." (PMID 36596773, 2023). "Antibodies targeting CD24 have been widely exploited for cancer treatment." (PMID 36882399, 2023). "Importantly, the positive populations for CSCs markers such as CD133, CD44, and CD24 were determined in the whole population of cancer cells." (PMID 37958844, 2023). "Therefore, CD24 should be considered when targeting the CD24–Siglec-10 axis for cancer immunotherapy." (PMID 37894750, 2023). "Supporting our speculation, RMS patient samples express several pluripotent cancer stem cell markers (CD24, CD133, Oct-4, Sox2, Nanog, and c-Myc) and are able to differentiate into neuronal cells, osteogenic cells, myocytes, and adipocytes." (PMID 37349371, 2023). "CD24 has been identified as a promising target for cancer immunotherapy, and targeting it with antibody drugs could offer effective treatment options." (PMID 38137380, 2023). "CD44 and CD24 are also used to characterize cancer stem cells." (PMID 37529165, 2023). "Consequently, cancer cells exhibiting CD24 surface expression are capable of evading immune cell surveillance and restrict the immune response via this mechanism." (PMID 38137380, 2023). "Further research into CD24 functions in these areas may reveal new insights and potential therapeutic applications beyond cancer." (PMID 38313430, 2023). "Recently, Lai reported that NPM/B23 could induce the expression level of CD24 in endometrial cancer cells to help cancer cells escape from the phagocytosis effect from macrophages." (PMID 37359556, 2023). "Due to its high expression in cancers and its role as a biomarker of some CSCs and an antiphagocytic checkpoint, CD24 may be a promising target for cancer immunotherapy." (PMID 36882399, 2023). "Notably, CD24 expression correlated with poor prognosis in several cancer types, including solid tumors and hematologic malignancies." (PMID 37894750, 2023). "In a co-culture model, stable genetic ablation of CD24 could increase the phagocytosis of cancer cells by Siglec-10 positive M2-like macrophages." (PMID 37359556, 2023). "Therefore, mTOR, STAT3, and CD24 were thought to represent promising and validated targets for the inhibition of cancer growth." (PMID 37919766, 2023). "Herein, we review the current understanding of the molecular fundamentals of CD24, the role of CD24 in tumorigenesis and cancer progression, the possibility as a promising therapeutic target and summarized different therapeutic agents or strategies targeting CD24 in solid cancers." (PMID 37919766, 2023). "Besides, knockdown of CD24 led to decreased expression of Notch1, to reduction in cancer stem cell properties as well as epithelial to mesenchymal transition." (PMID 37919766, 2023). "Therefore, there is an urgent need to develop new methods to treat cancer by altering the expression of CD24." (PMID 36866919, 2023). "Variations in CD24 expression levels can impact recurrence rates and survival in cancer patients." (PMID 37484024, 2023). "While this review has focused on how this pathway maybe fortified to treat or prevent inflammatory diseases, the role for CD24 in cancer therapy has also attracted significant interest." (PMID 37228622, 2023).
cancer (continued). "Furthermore, the clinicopathologic significance of CD24 is reported to be different even among the studies using the same type of carcinomas arising in the same organ." (PMID 37919766, 2023). "CD24 is a type of cell adhesion molecule participating in cell recognition, activation, signal transduction, proliferation, etc., which has been found to be abnormally expressed in various cancers." (PMID 35757760, 2022). "Indeed, CD24 has also been reported as a cancer stem cell marker, with CD24 regulating PI3K/Akt, STAT, or FAK signaling pathways." (PMID 35625912, 2022). "This could allow measuring multiple subpopulations of EVs presenting markers more specific for cancer-related EVs (such as CD24, CD44, or CD340)." (PMID 34935096, 2022). "Overexpression of CD24 has been found in various cancers, such as lung, breast, and ovarian." (PMID 34293822, 2022). "Third approach of TAM reprogramming is to promote antigen presentation and phagocytosis of TAMs by blocking anti-phagocytic surface proteins called “don’t eat me” signals, like SIRPα or Siglec-10, with antibodies blocking CD47 or CD24 expressed on cancer cells." (PMID 35211124, 2022). "In addition, we present clinical trials that have assessed the efficacy of CD24 blockade in cancer, either alone or in combination with other treatment modalities." (PMID 36013184, 2022). "CD24 has already been found to convey immune suppression in cancer." (PMID 36555567, 2022). "Thus, treatment of MCL cell lines with antibody-based CD24 targeting triggers extensive phagocytosis and a rapid decrease in cancer cell number in vitro." (PMID 35625912, 2022). "CD24, as a membrane protein, is involved in immune escape and cancer cell stemness, but could CD24 in the cytoplasm and nucleus play a biological function?" (PMID 36231025, 2022). "In addition, it has been reported that CD24 can be a major innate immune checkpoint in ovarian and breast cancers and a promising target for cancer immunotherapy." (PMID 36297672, 2022). "CD24 represents a promising target for cancer immunotherapy." (PMID 36013184, 2022). "Moreover, surface CD24 in cancer cells interacts with P- and E-selectins on activated endothelial cells and platelets, promoting rolling and translocation of malignant cells, leading to metastasis." (PMID 36294907, 2022). "Finally, the surface expression of CD24 in peripheral blood leukocytes has been shown to be both sensitive and specific for the detection of colorectal adenoma and cancer in individuals undergoing colonoscopy." (PMID 36013184, 2022). "At present, a large number of CD24 expressions have been found in a variety of cancers." (PMID 35330093, 2022). "CD24 can recruit integrin into lipid rafts that facilitate cancer development." (PMID 36042526, 2022). "In addition, cluster 4 and 1 expressed cancer stem cell-like cells (CSCLCs) gene markers CD24, CD44, and EPCAM, whereas cluster 0 and 2 expressed CD44 and NOTCH2, a gene marker denoted the activation of CSCLCs." (PMID 35733218, 2022). "Moreover, CEP192 was also discovered to be positively correlated with cancer stem cell markers including CD24, SOX9, CD47, and POU5F1 (OCT4)." (PMID 36238304, 2022). "However, CD24 has also recently been found to provide a unique immune escape mechanism utilized by a variety of cancer cells." (PMID 36031601, 2022). "CD24 and its ligand Siglec-10 were described as an innate immune checkpoint in carcinoma." (PMID 35625912, 2022). "As antibody clone SN3 potently induced phagocytosis of MCL cells, CD24/Siglec-10 checkpoint activity could exist in MCL similar to carcinoma." (PMID 35625912, 2022). "In addition, others have found that upregulation of CD24 is a poor prognostic factor for many cancer types." (PMID 33748077, 2021). "CD24 overexpression is positively correlated with the pathological grade or prognosis of cancer." (PMID 34363319, 2021). "CD24 is a mucin-like GPI-anchored molecule with a very broad role in the development of cancer." (PMID 33919517, 2021).